RETN (resistin)
Diseases named in the same sentence as RETN in open-access papers (continued):
Sharing a sentence is not in itself a finding about the gene and the disease.
ovarian carcinoma (continued). "Recombinant human resistin enhanced the expression of VEGF in a time‐ and dose‐dependent manner in human ovarian cancer cell lines." (PMID 37605299, 2023). "To further examine the effect of resistin on the progression of EOC, we treated two ovarian cancer cell lines, SKOV3 and CAOV3, with resistin." (PMID 34659568, 2021). "An important finding of our study is the establishment of a role of resistin in EMT and stemness of ovarian cancer cells." (PMID 30131543, 2018). "Previous results suggest that due to resistin’s key role in EOC proliferation and migration, it may be useful as a target for ovarian cancer treatment." (PMID 37190027, 2023). "In addition, it was shown that administration of exogenous resistin induced the proliferation of SKOV3 and CAOV3 ovarian cancer cells, while the administration of exogenous rapamycin, which is an inhibitor of resistin, inhibited their proliferation." (PMID 35453670, 2022). "In addition, it has been reported that resistin induced cellular proliferation, resistance to chemotherapy, and EMT (decreased E-cadherin and increased ZEB1 and vimentin levels) in ovarian cancer cells." (PMID 36291097, 2022). "Further, there is no report to-date reporting the levels of resistin in ovarian cancer patients, even though it is well regarded that resistin levels are generally elevated in cancer patients." (PMID 30131543, 2018). "Additionally, resistin induced EMT and stemness in the ovarian cancer cell lines A2780 and SKOV3." (PMID 35453670, 2022).
stable angina (13 papers, 2012 to 2025). "Patients with acute coronary syndrome had double the serum resistin levels compared to stable angina and control patients." (PMID 38255708, 2024). "We also noticed that resistin has an insignificant positive correlation with the CK-MB level in the stable angina group (r = 0.108, P-value=0.325) and a significant positive correlation in the AMI group (r = 0.444, P-value=0.025)." (PMID 34745775, 2021). "We also compared the level of resistin in stable angina versus AMI; there was a significant difference between them (P-value=0.0)." (PMID 34745775, 2021). "In stable angina, the resistin level was 8.368 ± 1.633 and the CK-MB level was 15.035± 2.05 while in AMI, the resistin level was 13.606 ± 2.067 and the CK-MB level was 42.89 ± 4.94." (PMID 34745775, 2021). "The resistin level in the serum of the control group was 2.427±1.252 ng/ml, its level in the stable angina group was 8.368 ± 1.633 ng/ml and in the AMI group, it was 13.606 ± 2.067 ng/ml." (PMID 34745775, 2021). "Many studies proved the positive correlation between resistin and CK-MB in stable angina and AMI patients." (PMID 34745775, 2021). "We found that resistin has a significant positive correlation with troponin-T level in the stable angina group (r = 0.498, P-value=0.013), and an insignificant positive correlation in the AMI group (r = 0.149, P-value=0.265)." (PMID 34745775, 2021). "Recent clinical studies indicated a positive correlation between high plasma levels of resistin and the severity of unstable angina (UA), atherosclerosis, and poor prognostic cases of coronary artery disease." (PMID 28286779, 2017). "A weak positive correlation was found between resistin and CK-MB in the stable angina group." (PMID 34745775, 2021). "The higher resistin levels in stable angina and AMI maybe because resistin is involved in thrombosis through its regulation of the endothelial nitric oxide synthase enzyme that plays a significant role in platelet aggregation, which leads to plaque formation." (PMID 34745775, 2021). "A weak positive correlation was found between SAA and resistin in the stable angina group." (PMID 34745775, 2021). "Among 2070 subjects, compared to disease-free controls, higher resistin levels were found among subjects with stable angina (standardized mean difference (SMD) = 1.97; 95% CI = 1.15–2.79), unstable angina (SMD = 2.54; 95% CI = 1.76–3.31) and MI (SMD = 3.62; 95% CI = 2.62–4.62)." (PMID 31940832, 2020). "In a study done to determine the levels of serum resistin between patients with stable and unstable angina it was found that plasma concentrations of resistin were significantly increased in unstable angina group in comparison with stable angina group and control groups." (PMID 24692844, 2014). "Moreover, a similar study demonstrated a significant increase in plasma resistin levels in patients with unstable angina when compared with patients with stable angina or control patients." (PMID 22910888, 2012). "Furthermore, blood resistin was positively correlated with indicators of inflammation and endothelial activation, such as leukocyte counts and endothelin-1 levels, in patients with unstable angina." (PMID 38255708, 2024). "A weak negative correlation was found between resistin and adiponectin in the stable angina group." (PMID 34745775, 2021). "In patients with stable angina treated by PCI, resistin levels increased at 12 hours after the procedure but did not correlate with the increases in troponins levels." (PMID 30405857, 2018).
breast tumor (12 papers, 2015 to 2022). "Overall, improved prognosis associated with increased resistin levels may indicate an immunomodulatory role of this protein during early breast tumour development limiting the ability of the tumour primary cells to spread to distant sites." (PMID 29566726, 2018). "Other studies have observed that the gene expression level of resistin is significantly enhanced in breast tumors of Black patients, and high resistin expression is associated with reduced survival and aggressive tumor characteristics." (PMID 29662629, 2018). "Inter-racial comparison of resistin gene expression between Caucasian American and African American breast tumors by stage/menopause status." (PMID 27314854, 2016). "Intra-racial comparison of resistin gene expression of Caucasian American and African American breast tumors by stage/menopause status." (PMID 27314854, 2016). "Notably, resistin expression was found to positively correlate with CXCL5 expression in the breast tumor tissues of the patients." (PMID 36104403, 2022). "We further explored the functional relevance between TAZ and Resistin in breast tumor progression." (PMID 33318171, 2020). "Some studies have proposed potential mechanisms connecting resistin with breast tumors." (PMID 26729407, 2016). "Moreover, the data also delineate molecular association of resistin and IL-6 at the regulatory level and establish STAT3 as a vital mediator in conferring the phenotypic response of resistin in breast tumor cells." (PMID 25868978, 2015). "In addition, resistin concentrations are positively correlated with malignancy, tumor stage and size and presence of metastasis, which makes this molecule a biomarker for breast tumor prognosis." (PMID 32903534, 2020). "In addition, the higher the resistin concentration, the worse the malignancy, tumor stage, size, and presence of metastasis, what justifies why it is considered a promising biomarker for breast tumor prognosis." (PMID 32903534, 2020). "Importantly, our findings linking resistin with LIN28A/Let-7a signaling axis are highly significant and add to our understanding of breast tumor biology." (PMID 34572725, 2021). "The present study aimed to evaluate the serum concentration of resistin in female dogs with CBMT, the most frequent histological type of breast tumor in this species, as well as its possible correlation with body condition, tumor aggressiveness, and survival rate." (PMID 32903534, 2020). "To explore the effect of resistin-stimulated ADSCs on breast tumor development in vivo, we collected the MDA-MB-231 cells after co-culture with R-ADSCs, or control ADSCs without resistin treatment, for xenograft implantation in the mammary fat pads of NOD/SCID mice." (PMID 36104403, 2022).
cardiac hypertrophy (12 papers, 2009 to 2026). "Silencing of autotaxin, platelet-derived growth factor D, resistin and microRNA-410-5P selectively and specifically only in adipose tissue ameliorates the development of cardiac hypertrophy and fibrosis, thus preventing experimental HFpEF." (PMID 41668130, 2026). "For instance, adenoviral-mediated overexpression of resistin in rodents led to marked cardiac dysfunction characterized by hypertrophy, impaired contractility, and pronounced myocardial fibrosis." (PMID 39682585, 2024). "Further, there are high resistin levels in cardiomyocytes derived from type 2 diabetic hearts, with resistin overexpression altering cardiac contractility and promoting cardiac hypertrophy potentially through the IRS1/MAPK pathway." (PMID 35069436, 2021). "Additionally, transgenic mice engineered to overexpress human resistin displayed significant cardiac hypertrophy, fibrosis, and diastolic dysfunction, reinforcing the hormone’s role in adverse cardiac remodeling." (PMID 39682585, 2024). "Studies in animal models have indicated that resistin may directly affect the myocardium, promoting cardiac hypertrophy and dysfunction." (PMID 34679472, 2021). "In this regard, effects on LVM may be through direct actions on the myocardium as cardiomyocyte overexpression of resistin promotes myocardial hypertrophy in mice." (PMID 32000666, 2020). "In accordance with other studies, echocardiographic traits of heart hypertrophy were positively associated with resistin in plasma, and there was a negative correlation with plasma adiponectin." (PMID 31533725, 2019).
colon cancer (12 papers, 2010 to 2022). "In addition, the resistin C-420G and G+299A polymorphisms have potential roles in the genetic predisposition to colon cancer." (PMID 33167521, 2020). "Given that inflammation is more strongly related to colon cancer than to rectal cancer, an examination by tumor subsite is important to better understand the impact of resistin as an exposure." (PMID 36428592, 2022). "For example, in colon cancer, resistin levels have been reported to be as high as 46.4 ng/mL in Dukes’ B1/B2 stage colon cancer and as high as 87.6 ng/mL in Dukes’ C/D stage colon cancer." (PMID 30131543, 2018). "For instance, our recent studies showed that resistin, which is primarily secreted by tumor-infiltrated host macrophages, arrests colon cancer cells in G1 phase and hampers 5-fluorouracil uptake." (PMID 30386595, 2018). "In humans, circulating resistin levels were greater in patients with colon cancer or colon adenoma compared with control subjects." (PMID 23304125, 2012). "We observed that circulating resistin levels were significantly increased in colon cancer patients as compared to controls." (PMID 21254741, 2010). "Despite these limitations we demonstrated that the levels of resistin and leptin were significantly different between colon cancer patients and controls." (PMID 21254741, 2010). "By contrast, resistin serum levels in colon cancer patients were significantly higher as compared to controls, both pre– and post operatively (P<0.001 in both cases)." (PMID 21254741, 2010). "Furthermore, it has been reported that high serum resistin levels correlate with tumor grade and poor prognosis in CRC patients, whereby resistin binds to Toll-like receptor 4 on the colon cancer cell membrane and promotes proinflammatory signalling pathways." (PMID 36361914, 2022). "Serum resistin levels in patients with colon cancer are elevated and correlated with tumor grade." (PMID 33167521, 2020). "Taken together, these results of this study suggest that adipokines, in particular resistin and leptin might be involved in development and progression of colon cancer." (PMID 21254741, 2010). "Also, an upregulation in 92% of the samples in the levels of resistin protein in colon cancer tissue was observed." (PMID 21254741, 2010). "Taken together, these results of this study suggest that adipokines, in particular resistin and leptin may be involved in development and progression of colon cancer." (PMID 21254741, 2010). "In our study, although colon cancer patients displayed increased serum resistin levels, we did not obtain any correlation between serum levels of resistin and tumor stage, localization or grade of differentiation." (PMID 21254741, 2010). "Collectively, our results showed a statistically significant increase in resistin serum levels but a lack of direct involvement of resistin in the systemic inflammatory response of patients with colon cancer or in disease progression." (PMID 21254741, 2010). "Further limitations are the small sample size and the associated lack of significance in statistical analysis of the data and the lack of correlation of resistin levels with tumor size based on T-staging and tumor grading in patients suffering from colon cancer." (PMID 23173608, 2012).
Impaired glucose tolerance (12 papers, 2009 to 2023). An abnormal resistance to glucose, i.e., a reduction in the ability to maintain glucose levels in the blood stream within normal limits following oral or intravenous administration of glucose. "In obesity and insulin resistance, the role of resistin is as yet highly controversial, although its function has been associated with impaired glucose tolerance." (PMID 22550485, 2012). "In addition, mice under chronic variable stress and fed with a high-fat diet showed impaired glucose tolerance associated with low plasma adiponectin-resistin ratios." (PMID 21251282, 2011). "Resistin appears to play an important role in GDM and possibly the pathogenesis of impaired glucose tolerance, and increased maternal resistin levels could be associated with the presence of maternal PE." (PMID 37239090, 2023). "Consistent with the impaired glucose tolerance, HOMA-IR, and QUICKI in NA/STZ-induced diabetic rats, the present results showed a significant elevation in adipose tissue resistin mRNA expression as compared to the control group." (PMID 32047529, 2020). "With regard to pGDM, one study showed that resistin was significantly higher 18 months postpartum in women with normal or impaired glucose tolerance who had pGDM compared to a group of women who did not develop DM during pregnancy." (PMID 22550485, 2012).
inflammatory bowel disease (12 papers, 2008 to 2024). A spectrum of small and large bowel inflammatory diseases of unknown etiology. "Similar profile of serum adipokine concentrations that is elevated Acrp30 and resistin, and decreased leptin was reported in patients with inflammatory bowel disease." (PMID 24259947, 2013). "An association between resistin and inflammation has been reported in several different diseases, including RA and inflammatory bowel disease, but is very weak or nonexistent in studies of apparently healthy individuals." (PMID 18234104, 2008).
ischemic stroke (12 papers, 2009 to 2024). A stroke disorder caused by obstruction of blood flow to the brain, due to thrombotic (local blood clot formation) or embolic (due to a blood clot or other material traveling from another site) event. "The PRIME study found that resistin provided an additive value together with the classic risk factors in predicting ischemic stroke in a large cohort of 9771 patients." (PMID 36745280, 2023). "The Hisayama study showed that high serum resistin levels are associated with the risk of ischemic stroke in peoples with diabetes and hypertension." (PMID 36745280, 2023). "Gender and age differences also exist, as in postmenopausal women, where high resistin levels are associated with an increased risk of ischemic stroke." (PMID 34445740, 2021). "After adjusting for body mass index (BMI) and other ischemic stroke risk factors, resistin was the only adipokine found to predict the odds of ischemic stroke (mOR, 1.61; 95% CI, 1.22-2.13; p<0.001)." (PMID 31127075, 2019). "The studies included in this review found that several serologic markers, including CML, CRP, tHcy, estradiol, DHT and resistin, are associated with an increased risk of ischemic stroke." (PMID 31127075, 2019). "A second case-control study enrolled post-menopausal women who had experienced an ischemic stroke and assessed the association with three plasma-based adipokines: adiponectin, leptin, and resistin." (PMID 31127075, 2019). "In the patients with ischemic stroke, high plasma resistin level has been associated with mortality and disability." (PMID 21029428, 2010). "Elevated serum resistin concentration appears to be an independent risk factor for ischemic stroke, especially lacunar and atherothrombotic infarction in the general Japanese population." (PMID 19922611, 2009). "Serum resistin concentration was a risk factor for ischemic stroke, especially lacunar and atherothrombotic infarction, and the association was independent of traditional confounding factors and hs-CRP." (PMID 19922611, 2009). "Our findings suggest that elevated serum resistin concentration is a significant risk factor for ischemic stroke in a general Japanese population." (PMID 19922611, 2009). "The risk of ischemic stroke markedly increased in diabetic subjects with high resistin (OR: 5.88; 95% CI: 2.82-12.26; p < 0.001)." (PMID 19922611, 2009). "Elevated resistin was an independent risk factor for ischemic stroke even after adjustment for confounding factors including hs-CRP." (PMID 19922611, 2009). "On the other hand, resistin has been associated with pro-inflammatory effects and an increased risk of ischemic stroke and atherogenesis, with described associations between this adipokine and unstable carotid plaques, as well as intracranial stenosis and associated vascular events." (PMID 39339817, 2024). "Furthermore, diabetic subjects with high resistin had greater risk of ischemic stroke than diabetic subjects with low resistin (p < 0.05)." (PMID 19922611, 2009). "Thus, our findings regarding the association between each subtype of ischemic stroke and serum resistin is reasonably consistent with the known pathology." (PMID 19922611, 2009). "In hypertensive subjects, high resistin was associated with risk of ischemic stroke (p < 0.05)." (PMID 19922611, 2009). "It is well known that high plasma resistin levels may be strongly associated with an increased risk of 5-year mortality or disability after atherothrombotic ischemic stroke as well as related to 1-week mortality after acute spontaneous basal ganglia hemorrhage." (PMID 21029428, 2010). "Resistin is an adipocytokine produced by adipocytes that has been shown to be a promising prognostic marker in lacunar ischemic stroke." (PMID 39777314, 2024). "In the early phase of an acute ischemic stroke, high resistin values were found, indifferent of age or sex." (PMID 34445740, 2021).